MIR2114 (microRNA 2114)
Synonyms: hsa-mir-2114
Gene: MicroRNA gene on chromosome X (150,228,004 to 150,228,083, forward strand). Ensembl gene ENSG00000252454.
Homologues: Orthologues: chimpanzee MIR2114 (100% identical).